WDR87 (WD repeat domain 87)
Synonyms: NYD-SP11
Tractability: PROTAC: ubiquitination databases record sites on it.
Gene: Protein-coding gene on chromosome 19 (37,884,823 to 37,906,677, reverse strand). Ensembl gene ENSG00000171804.
Genetic constraint (gnomAD): Loss-of-function variants: 51 observed, 83.5 expected, observed/expected ratio (o/e) 0.61, 90% interval 0.49 to 0.77. The upper end of that interval is the gene's LOEUF score, 0.77, which puts it in group 3 of 6, group 1 being the genes least tolerant of losing a copy. Missense variants: 2,866 observed, 3,467.2 expected, observed/expected ratio (o/e) 0.83, 90% interval 0.8 to 0.85. Synonymous variants: 1,143 observed, 1,269.7 expected, observed/expected ratio (o/e) 0.9, 90% interval 0.86 to 0.94.
Homologues: Orthologues: chimpanzee WDR87 (98% identical), macaque WDR87 (92% identical). Paralogues in human: WDR25 (3% identical), CDC40 (3% identical).
Diseases named in the same sentence as WDR87 in open-access papers:
WDR87 is named in the same sentence as 5 diseases in open-access papers, as found by Europe PMC text mining. Sharing a sentence is not in itself a finding about the gene and the disease. The quoted sentences say what the papers report.
cervical cancer (1 paper, 2021). A primary or metastatic malignant neoplasm involving the cervix. "To investigate the functional implications of WDR87 amplification, we performed transient transfection of WDR87 constructs into a cervical cancer cell line CRL1595 and an immortalized embryonic kidney cell line HA1E." (PMID 34620846, 2021).
tumor (2 papers, 2018 to 2021). "In addition, we performed functional experiments and demonstrated that overexpression of WDR87 increased cellular proliferation within both cell lines investigated, suggesting that this protein may in fact have tumor-promoting properties." (PMID 34620846, 2021). "We expected that the four genes (SACS, LRP2, WDR87, and XIRP2) that were detected in all POLE category tumours with POLE p.P286R or p.V411L would exhibit high PS if this score reflected an accumulation of biased mutation patterns." (PMID 29880869, 2018).
WDR87 also shares sentences with these, for which no sentence is quoted: cancer (1 paper); dengue (1); metastatic prostate carcinoma (1).